ICAM1 (intercellular adhesion molecule 1)
Diseases named in the same sentence as ICAM1 in open-access papers (continued):
Sharing a sentence is not in itself a finding about the gene and the disease.
breast carcinoma (continued). "We have been investigating the mechanism of cell migration in the Luminal B breast cancer cell lines MCF7 and T47D, and were the first to demonstrate that MUC1 mediates heterotypic cell-cell adhesion by binding ICAM-1, which is expressed on peritumoral stromal and endothelial cells." (PMID 21798038, 2011). "Similarly, the elevated levels of ICAM-1 (Intercellular Adhesion Molecule – 1) and decay-accelerating factor (DAF/CD55) in cancers like breast cancer, multiple myeloma, and melanoma allow coxsackievirus (e.g., coxsackievirus A21) to induce oncolysis within these malignancies." (PMID 41313526, 2025). "The downregulation of ICAM-1 in MYCN-A neuroblastoma discovered here is particularly noteworthy, given its association with reduced NK cell cytotoxicity and immune escape in other tumors, such as breast cancer." (PMID 39860532, 2025). "We hypothesized that ICAM-1 may be a specific marker for TNBC based on the analysis results, which demonstrated that ICAM-1 was significantly highly expressed in the basal-like breast cancer subtypes and that ICAM-1 expression was highest in the PR-negative group and ER-negative group." (PMID 38799250, 2024). "Secondly, when we analyzed the sub-cellular localization of ICAM1, only breast cancer samples could be selected because no TNBC samples related to ICAM1 expression were retrieved from the HPA database; this may affect the analysis results." (PMID 37671167, 2023). "In breast cancer cells, these EMT-promoting transcription factors are known to induce the production of GM-CSF and other inflammatory cytokines such as IL-6, IL-8, soluble intercellular adhesion molecule 1 (ICAM1), and plasminogen activator inhibitor 1 (PAI1) and enhance cancer progression." (PMID 35865534, 2022). "Our findings suggest that the growth of these breast cancer cells in primary orthotopic tumors is not affected by ICAM-1 deletion, whereas the ability of these breast cancer cells to give rise to metastatic lesions in the lungs is dramatically increased in the absence of ICAM-1." (PMID 35911772, 2022). "The in vivo elimination of a primary E0771 tumor expressing the ovalbumin (OVA) model neoantigen by the OVA-specific OVA-tcr-I mice (OT-I) transgenic cytotoxic T lymphocytes (CTLs) also took place normally in the absence of ICAM-1 expression by E0771 breast cancer target cells." (PMID 35911772, 2022). "The surface ICAM1 expression of two human TNBC cell lines (MDA-MB-231 and MDA-MB-468), ER-positive breast cancer cell line MCF-7, MDA-MB-231 ICAM1KO cell line, normal human mammary epithelial MCF10a, and HER2-amplified luminal breast cancer cell line SKBR3 were examined by FACS." (PMID 33072116, 2020). "In addition, HER2-amplified luminal breast cancer cell line SKBR3 cells (ICAM1 negative) were selected as control cells in our study." (PMID 33072116, 2020). "PDIA1-dependent regulation of cancer–endothelial cell interactions involves disulphide exchange and most likely integrin activation but is not mediated by the regulation of ICAM-1 expression or changes in cellular bioenergetics in breast cancer or endothelial cells." (PMID 33023153, 2020). "Furthermore, ICAM1 might be involved in cancer metastasis, as shown by silencing of ICAM1 in MCF7 breast cancer cells." (PMID 30082828, 2018). "To determine whether expression of ICAM-1 is altered in different subtypes of breast cancer, we evaluated the level of ICAM-1 in metastatic cancer cells and non-metastatic cells." (PMID 29137327, 2017). "Additionally, we confirmed that knockdown of FBXO4 alone or co-knockdown of FBXO4 and ICAM-1 reversed these effects in non-metastatic breast cancer cells." (PMID 29137327, 2017). "However, the mechanism by which OPN regulates ICAM-1 expression in breast cancer cells is not well defined." (PMID 20459645, 2010).
breast carcinoma (continued). "Additionally, we found that four of these sEV surface proteins (CTTN, FSCN1, ICAM1, MMP14) were exclusively present in sEVs from high invadopodia activity cells, which have previously been reported in sEVs that are preferentially secreted from invadopodia in breast cancer cells." (PMID 37014551, 2023). "A liposomal formulation with an antibody targeting intercellular adhesion molecule-1 (ICAM) loaded with siRNA-LCN2 has previously shown stronger binding and internalization in triple-negative MDA-MB-231 breast cancer cells than in non-cancerous cells." (PMID 40732340, 2025). "Moreover, an increase in the serum levels of biomarkers (i.e., ICAM-1, PECAM-1, NSE) and changes in functional connectivity together might indicate a complex lesion of the central nervous system in VAS in patients in the long-term period following breast cancer treatment." (PMID 37368372, 2023). "To understand how FBXO4 modulates ICAM-1 stability, we investigated ICAM-1-overexpressing or knockdown metastatic/non-metastatic breast cancers." (PMID 29137327, 2017). "While, overexpressing of ICAM-1 were increased the expression of vimentin and ZEB in non-metastatic breast cancer cells." (PMID 29137327, 2017). "In lung and breast cancer cells, leptin treatment has amplified the levels of soluble ICAM-1 by upregulating ERK, GSK3αβ, JAK1/2, STAT3 and focal adhesion kinase (FAK) signaling without affecting the expression of cell surface ICAM-1." (PMID 34588926, 2021). "In contrast to nontreated con cells, for senescent human breast cancer MDA-MB-231 cells, the factors detected by arrays and secreted at a significant level are FGF-6, GM-CSF, IGFBP-1, MCP-1, IL-6, IL-1α, GRO a/b/g, GRO α, IL-8, MIP, MIP-1α, uPAR, ICAM-1, and MMP-1." (PMID 30871042, 2019).
Sepsis (187 papers, 2007 to 2026). Sepsis is defined as life-threatening organ dysfunction caused by a dysregulated host response to infection. "A previous study has shown that PHD3-deficient mice treated with LPS exhibited increased susceptibility to sepsis, increased pro-inflammatory cytokine release, enhanced macrophage activity, and elevated levels of NFκB and ICAM1." (PMID 40003076, 2025). "Investigating the role of these antibiotic-induced BEVs in driving ICAM-1 upregulation is vital, as this process can exacerbate inflammation and contribute to endothelial dysfunction, a hallmark of sepsis pathogenesis." (PMID 40463015, 2025). "By sequestering miR-150-5p, MALAT1 upregulates intercellular adhesion molecule 1 (ICAM-1) expression, worsening pulmonary inflammation in sepsis-associated ALI." (PMID 40868190, 2025). "In patients with sepsis, increased ICAM-1 and VCAM-1 levels have been associated with organ dysfunction and mortality." (PMID 39409009, 2024). "In accordance with our observation, in a previous study in adult murine model of polymicrobial sepsis, ICAM-1-deficient mice demonstrated a significant reduction of mortality compared to WT mice." (PMID 38263289, 2024). "Downregulation of ICAM1 expression is potentially highly significant in certain diseases considering the protective role of ICAM1 deficiency in sepsis-related mortality." (PMID 38396987, 2024). "GEE results revealed that zone 1 ROP, stage 3 ROP, older baseline PMA, RDS, NEC, and sepsis were associated with increases or decreases in the serum levels of GM-CSF, IL-5, IL-15, ICAM-1, TNF-α, and TNFR-2 in premature infants." (PMID 38259597, 2023). "Circulating ICAM-1, a marker of endothelial damage, has been documented to be elevated in sepsis and COVID-19 patients, with higher levels associated with increased severity." (PMID 37822940, 2023). "Leukocyte adhesion to the vasculature and expression of VCAM-1 and ICAM-1 are associated with the development of multiple organ failure in severe sepsis." (PMID 35145983, 2022). "Platelet-derived microparticles (PMPs) carry miR-223 to endothelial cells and maintain intercellular adhesion molecule-1 (ICAM-1) at low levels under septic conditions, thus avoiding excessive sepsis-associated vascular inflammation." (PMID 34956210, 2021). "The ICAM-1 (CD54) is highly expressed on the pulmonary endothelial cells, pulmonary macrophages, and lymphocytes in sepsis-associated fatalities." (PMID 32849610, 2020). "The present study aims to assess the diagnostic value of intercellular adhesion molecule-1 (ICAM-1) in individuals with sepsis." (PMID 31192950, 2019). "The diagnostic value of ICAM-1 in sepsis has been reported in several studies; however, these results are variable." (PMID 31192950, 2019). "But two studies published in 2005 and 2006 demonstrated a protective role of ICAM-1 deficiency in polymicrobial sepsis." (PMID 24891762, 2014). "Consistent with these published reports, our results show that sepsis is associated with elevated circulating levels of soluble ICAM-1, VCAM-1 and E-selectin." (PMID 20942957, 2010). "Moreover, a review has confirmed that five different soluble adhesion molecules are associated with the presence of sepsis, specifically, E-selectin, L-selectin, P-selectin, ICAM-1, and VCAM-1." (PMID 38153527, 2024). "Martijn van Griensven observed that ICAM-1 had a strong pathogenic effect on sepsis." (PMID 37779910, 2023). "Sepsis is associated with upregulation of endothelial cell adhesion molecules including ICAM-1 and VCAM-1, and this mechanism may also contribute to the accumulation of monocytes within plaques following pneumonia." (PMID 37033482, 2023). "We show that in sepsis patients, ageing was associated with a striking decrease of all measured endothelial cell activation markers (soluble E-selectin, soluble ICAM-1, fractalkine), an increase in angiopoietin-1 concentrations and a decrease of the angiopoietin-2/1 ratio." (PMID 36514130, 2022).
Sepsis (continued). "In neonates with sepsis, nutritional supplementation with a lipid emulsion consisting of MCT, olive, fish, and soy oil for 7 days led to increased soluble intercellular adhesion molecule 1 (sICAM1) and leukocyte β2 integrin, which are both associated with improved sepsis outcomes." (PMID 35433045, 2022). "A recent study showed that CIRP could promote the development of the ICAM‐1+ neutrophils, which has the properties of producing high levels of ROS during sepsis to cause injury to the lung." (PMID 34953031, 2022). "ICAM-1, an important intercellular adhesion molecule, has been implicated in inflammatory process and the transmigration of polymorphonuclear neutrophils in sepsis." (PMID 28415764, 2017). "It was reported that inhibition of ICAM-1 expression in lungs was associated with improvement of sepsis induced by cecal ligation and puncture (CLP) in mice, when they were treated by some agents such as protein kinase C-delta, hypertonic saline solution, and perfluorocarbon." (PMID 24891762, 2014). "Indeed, ICAM-1-deficient mice are protected from experimental sepsis-induced AKI." (PMID 20064258, 2010). "This study aims to explore the mechanism of ubiquitin-specific peptidase 7 (USP7) in sepsis with the involvement of intercellular adhesion molecule-1 (ICAM-1)." (PMID 41170880, 2025). "Elevated levels of soluble intercellular adhesion molecule-1 (ICAM-1) and soluble vascular cell adhesion molecule-1 (VCAM-1) have been observed in patients with sepsis and are associated with worse clinical outcomes." (PMID 39821561, 2025). "This amount of LPS is over twenty times the concentration that has been observed in patient serum during sepsis, and should therefore elicit a consistently high ICAM-1 response." (PMID 40463015, 2025). "This assumption was supported for example by VCAM1 and ICAM1, which at day 1 showed the lowest levels in cluster 3 (regulation pattern α), and for which increasing plasma levels are well known to be related to sepsis severity." (PMID 40898225, 2025). "In sepsis, ECs become activated, leading to an increase in the expression of various adhesion molecules such as ICAM-1, VCAM-1, E-selectin, P-selectin, and vWF." (PMID 39974277, 2025). "Consistently, this study found that in both sepsis and COVID-19, the inflammatory response resulted in ICAM1 upregulation, further leading to acute lung injury (ALI)." (PMID 41411324, 2025). "During sepsis, activated ECs upregulate the expression of adhesion molecules, including the β2-integrin ligand intercellular adhesion molecule-1 (ICAM-1)." (PMID 40226627, 2025). "Integrins mediate the stable adhesion of neutrophils to ECs by binding to up-regulated ICAM-1 on ECs during sepsis." (PMID 40226627, 2025). "EC ICAM‐1 expression, IL‐6 and soluble ICAM‐1 secretion increased significantly more after incubation with sepsis plasma compared with healthy plasma." (PMID 38981846, 2024). "ICAM-1 is typically expressed at low levels; however, its expression is up-regulated during sepsis and inflammatory conditions, increasing the leukocytes adhesion." (PMID 38637839, 2024). "GdCl3 pretreatment in mice with CLP-induced sepsis attenuated the increase in ICAM-1 concentration in the liver." (PMID 38254684, 2024). "In mice with CLP-induced sepsis, immunofluorescence microscopy showed higher immunoreactivity of ICAM-1 and VCAM-1 that co-localized with structures identified by CD31 staining than in sham-operated control mice." (PMID 38254684, 2024). "ICAM-1 expressed in capillary-1 cells has stronger interaction with neutrophil than ICAM-1 expressed in capillary-2 cells, which mediates neutrophil adhesion during sepsis." (PMID 38348045, 2024). "In a mouse model of sepsis, an association between BBB disruption and ICAM-1 induction was demonstrated." (PMID 36979834, 2023). "A critical factor in this process is ICAM-1, a molecule that increases during sepsis alongside other pro-inflammatory cytokines." (PMID 38406786, 2023).
Sepsis (continued). "Studies in animal models have demonstrated that endothelial ICAM-1 expression is upregulated during sepsis, and there is also a transient increase in VCAM-1." (PMID 37048076, 2023). "In an in vitro experimental model of sepsis, there was progressive endothelial cell activation in correlation with the severity of sepsis, with significantly increased expression of surface adhesion receptors, such as ICAM-1, VCAM-1 and vWF, etc.." (PMID 37700349, 2023). "The reduced (from baseline) serum level of ICAM-1 at week 4 was significantly associated with zone 1 ROP, RDS, and sepsis in our patients." (PMID 38259597, 2023). "VCAM-1 and ICAM-1 are markers of vascular endothelial damage in sepsis and can be used to monitor the development of organ dysfunction, such as kidney injury." (PMID 37779910, 2023). "A reduction in the serum level of ICAM-1 was associated with RDS (p < 0.0001) and sepsis (p = 0.0457)." (PMID 38259597, 2023). "During sepsis, ICAM-1+ neutrophils increase in number and accumulate in lung tissue, leading to ARDS." (PMID 37553691, 2023). "These factors complexify the relationship between soluble ICAM-1 levels and clinical outcomes in sepsis." (PMID 37237555, 2023). "The pooled mean concentration of ICAM-1 was significantly higher in patients with SAE compared to the patients with sepsis alone (SMD 0.41; 95% CI 0.05–0.76; p = 0.03)." (PMID 36802387, 2023). "qPCR and Western blotting demonstrated that the mRNA and protein levels of VCAM-1 and ICAM-1, induced by sepsis, were elevated, but this elevation was mitigated by echinacoside treatment." (PMID 38001778, 2023). "ICAM-1 is known to be increased in septic shock patients, and models of experimental sepsis have demonstrated a less severe clinical course and improved survival rates in ICAM-1-knockout mice." (PMID 37946314, 2023). "Endothelial activation in sepsis leads to the expression of E- and P-selectin, VCAM-1, and ICAM-1 on the endothelial cell surface, which in turn causes leukocytes to roll, adhere, and transmigrate across the endothelial cells." (PMID 37700349, 2023). "Genetic ablation of the adhesion molecule ICAM-1 improved survival in murine sepsis by attenuating neutrophil infiltration into the lungs and preventing lung injury." (PMID 35625756, 2022). "Collectively, these results suggest that CIRP plays a key role in regulating iNOS‐producing and NET‐forming ICAM‐1+ neutrophils in the lungs during sepsis." (PMID 34953031, 2022). "The level of ICAM-1 and u-Plasminogen Activator was significantly increased in sepsis patients compared with SIRS patients throughout the study period." (PMID 35363162, 2022). "In a likely attempt by the body to control and cool down the system, PEVs in sepsis are also enriched in miR-223 which reduces intracellular adhesion molecule 1 (ICAM-1)-dependent vascular inflammation in sepsis." (PMID 35887184, 2022). "We found that the endothelial functional markers of Urokinase, ICAM-1 and VEGFR2 were the potential diagnostic tools in patients with suspected sepsis." (PMID 35363162, 2022). "Leukocyte adhesion and mRNA and protein expression of VCAM-1 and ICAM-1 were significantly increased in the sepsis serum group compared to that in the control group, as was the protein expression of p-p38 and p-ERK1/2." (PMID 35145983, 2022). "Although ICAM-1 appears to be important in the etiology of sepsis, the regulatory mechanisms of ICAM-1 expression in sepsis is not well known." (PMID 36614145, 2022). "We performed multivariate logistic regression analysis among SIRS and sepsis patient, found that the levels of Urokinase, ICAM-1, and VEGFR2 were independent predictors for diagnosis after multivatiate analysis." (PMID 35363162, 2022). "VCAM-1 (1.004 ± 0.06 vs. 4.508 ± 0.840, p < 0.05) and ICAM-1 (1.001 ± 0.04 vs. 3.552 ± 0.04, p < 0.05) mRNA expression was significantly increased in sepsis serum-treated HUVECs compared to the control group." (PMID 35145983, 2022).